ANGPTL6 (angiopoietin like 6)
Description:
May play a role in the wound healing process. May promote epidermal proliferation, remodeling and regeneration. May promote the chemotactic activity of endothelial cells and induce neovascularization. May counteract high-fat diet-induced obesity and related insulin resistance through increased energy expenditure.
Synonyms: AGF; ARP5
Tractability: Antibody: UniProt places it where antibodies can reach, with high confidence; UniProt predicts a signal peptide or a membrane-spanning region; its Gene Ontology location is reachable by antibodies, with medium confidence.
Gene: Protein-coding gene on chromosome 19 (10,092,337 to 10,106,612, reverse strand). Ensembl gene ENSG00000130812.
Subcellular location: Secreted
Gene Ontology:
Molecular function: signaling receptor binding
Biological process: blood coagulation
Cellular component: extracellular exosome; extracellular matrix; extracellular region; secretory granule
Genetic constraint (gnomAD): Loss-of-function variants: 45 observed, 43.11 expected, observed/expected ratio (o/e) 1.04, 90% interval 0.82 to 1.34. The synonymous counts are far from expectation, so gnomAD's model fits this gene poorly and the ratio says little. Missense variants: 698 observed, 582.34 expected, observed/expected ratio (o/e) 1.2, 90% interval 1.13 to 1.28. Synonymous variants: 290 observed, 235.4 expected, observed/expected ratio (o/e) 1.23, 90% interval 1.12 to 1.36.
Homologues: Orthologues: chimpanzee ANGPTL6 (99% identical), macaque ANGPTL6 (97% identical), dog ANGPTL6 (90% identical), pig ANGPTL6 (89% identical), guinea pig ANGPTL6 (86% identical), rat Angptl6 (74% identical), mouse Angptl6 (74% identical), tropical clawed frog angptl6 (46% identical), zebrafish angptl6 (45% identical). Paralogues in human: ANGPTL2 (45% identical), ANGPTL1 (42% identical), ANGPT4 (28% identical), ANGPT1 (27% identical), TNC (26% identical), TNR (26% identical), ANGPT2 (26% identical), TNXB (26% identical), FGB (25% identical), FIBCD1 (24% identical), FGG (23% identical), TNN (23% identical), and 13 more.
Diseases named in the same sentence as ANGPTL6 in open-access papers:
ANGPTL6 is named in the same sentence as 43 diseases in open-access papers, as found by Europe PMC text mining. Sharing a sentence is not in itself a finding about the gene and the disease. The quoted sentences say what the papers report.
Obesity (22 papers, 2010 to 2025). Accumulation of substantial excess body fat. "An animal knockout model provided further evidence highlighting the association between ANGPTL6 levels and diabetes, where the targeted disruption of the ANGPTL6 gene led to obesity and insulin resistance in mice." (PMID 32277104, 2020). "ANGPTL6 was associated with an increased risk of T2D (adjusted OR [95% CI] = 1.04 [1.01–1.08]) and obesity (adjusted OR [95% CI]= 1.03 [1.01–1.06])." (PMID 32277104, 2020). "Multivariate logistic regression analysis was performed to ascertain the association between MPO, ANGPTL6 and the outcome of T2D and obesity." (PMID 32277104, 2020). "ANGPTL6/Angiopoietin-related growth factor (AGF)-deficient mice develop severe obesity and insulin resistance accompanied by reduced energy expenditure relative to controls." (PMID 26132105, 2015). "Thus, this study aimed to evaluate the plasma MPO and ANGPTL6 levels in both obese and T2D patients and to assess their association with the biochemical markers of obesity, inflammation, and atherosclerosis." (PMID 32277104, 2020). "Further validation in cohorts with severe obesity and engineering the variants in model organisms will be needed to explore whether human variants in ANGPTL6 and other genes that lead to obesity when deleted in mice, do contribute to obesity." (PMID 28663568, 2017). "Furthermore, ANGPTL6 was associated with an increased risk of T2D and obesity." (PMID 32277104, 2020). "ANGPTL6 is also mainly secreted by the liver, and a higher incidence of obesity, diabetes, fat accumulation in liver and muscle, and insulin resistance have been observed in mice lacking this protein." (PMID 39409124, 2024). "As studies have shown higher levels of this protein in patients with obesity and T2D, the existence of ANGPTL6 resistance in these conditions has been suggested." (PMID 39409124, 2024). "Most recent data in humans indicate that subjects with obesity and/or type 2 diabetes have higher blood levels of ANGPTL6 compared with controls." (PMID 37274345, 2023). "By contrast, knockout mice for ANGPTL6 show an increased incidence of obesity, insulin resistance, and increased fat content in peripheral organs (especially the liver and skeletal muscle)." (PMID 37274345, 2023). "Activation of ANGPTL6, also known as an angiopoietin-related growth factor, has been associated with several beneficial metabolic effects such as protection from steatosis, insulin resistance, and HFD-induced obesity." (PMID 36769005, 2023). "It is encoded by the angiopoietin-like protein 6 gene (ANGPTL6, OMIM*609336) and is capable of counteracting both obesity and obesity-related insulin resistance." (PMID 36143124, 2022). "Previous studies revealed increased serum concentrations of this anti-obesity hepatokine in individuals with metabolic syndrome and type 2 diabetes and decreased circulating ANGPTL6 levels in hemodialyzed individuals compared to healthy subjects." (PMID 36143124, 2022). "ANGPTL6 is highly expressed in obesity, augmented lipid accumulation in skeletal muscle and liver, reduced energy expenditure, and increased insulin resistance." (PMID 33807959, 2021). "This study aims to evaluate the plasma MPO and ANGPTL6 levels in obese and diabetic individuals as well as MPO association with biochemical markers of obesity." (PMID 32277104, 2020). "After classifying patients with T2D according to obesity status, our findings showed that both plasma ANGPTL6 and MPO levels were significantly higher in obese than in non-obese diabetic patients." (PMID 32277104, 2020). "In this study, the role of MPO and ANGPTL6 on diabetes and obesity was assessed, and results showed that although both markers are elevated in obese participants, diabetes status can affect their physiological function." (PMID 32277104, 2020).
Obesity (continued). "Conversely, ANGPTL6 had been shown to negatively correlate with obesity and insulin resistance, alongside a marked increase in energy expenditure, in a manner independent of lipoprotein lipase and lipid metabolism regulation." (PMID 31396158, 2019). "Mice with genetic ablation of Angptl6 exhibited greater obesity phenotypes, with increased hepatic fat accumulation and insulin resistance, in conjunction with impaired energy utilization, while Angptl6 overexpression improved hepatic steatosis and obesity under increased energy expenditure." (PMID 34944728, 2021). "Thus, further longitudinal studies about the causal relationship between ANGPTL6 and MPO in T2D and obesity must be conducted." (PMID 32277104, 2020). "Thus, future studies should evaluate the beneficial effects of targeting MPO and ANGPTL6 simultaneously for the treatment of both obesity and T2D by inhibiting the activity of MPO and overexpression of ANGPTL6." (PMID 32277104, 2020). "Interestingly, mice knockout studies have shown that ANGPTL6 counteracts diet-induced obesity and insulin resistance via increasing energy expenditure, which suggests that ANGPTL6 may have a modulatory role in diabetes." (PMID 36143124, 2022). "The present study aimed to determine the plasma ANGPTL6 and MPO levels in both obese and diabetic individuals to validate their role in these conditions and to assess any association between MPO levels and the markers of obesity, inflammation, and atherosclerosis." (PMID 32277104, 2020). "Also ANGPTL-6 is playing a protective effect by antagonizing obesity and IR." (PMID 31170218, 2019). "Angiopoietin-like protein 6 (ANGPTL6) regulates metabolic processes and counteract obesity through increased energy expenditure." (PMID 32277104, 2020). "Multiple members of this protein family are closely related to obesity and obesity-related metabolic diseases: ﻿ANGPTL3, ANGPTL4, and ANGPTL6 can directly regulate lipid, glucose, and energy metabolism without exerting angiogenic effects." (PMID 32299395, 2020). "We show that the CR increased the expression levels of anti-inflammatory genes Il-10 and Adrbk1 and energy homeostasis-related genes such as Ptgds, Lpin2, Angptl6, Kcnj11, and Dusp9 but were not affected by obesity in HF mice." (PMID 20307313, 2010). "Interestingly, after classifying healthy participants (non-diabetics) according to obesity status in this study, the plasma ANGPTL6 levels did not significantly differ between obese and non-obese participants, indicating that it may be dependent on the diabetes status." (PMID 32277104, 2020). "First, the mechanism of ANGPTL6 and MPO in obesity or T2D was not identified due to the cross-sectional design of the study." (PMID 32277104, 2020). "Taken together, our findings suggest that both MPO and ANGPTL6 may regulate obesity, although MPO exerts this effect independent of diabetes while ANGPTL6 may have a modulatory role in diabetes." (PMID 32277104, 2020). "However, the role of both ANGPTL6 and MPO in both obesity and diabetes in humans has not been determined." (PMID 32277104, 2020).
Insulin resistance (13 papers, 2015 to 2025). Increased resistance towards insulin, that is, diminished effectiveness of insulin in reducing blood glucose levels. "ANGPTL4 negatively correlates with circulating triglycerides and is linked with metabolic syndrome and T2D, whilst ANGPTL6 is elevated in T2D subjects and correlates with insulin resistance." (PMID 37810875, 2023). "As reviewed previously, ANGPTL2 primarily derived from visceral fat is positively associated with inflammation and insulin resistance, while ANGPTL6 expressed in the liver is found to counteract obesity and insulin resistance by suppressing gluconeogenesis and enhancing energy expenditure." (PMID 35693558, 2022). "ANGPTL6 could therefore contribute to the development of diabetic nephropathy through pathways related to insulin resistance, which is associated with greater salt sensitivity, increased glomerular pressure, albuminuria, and kidney function decline." (PMID 36143124, 2022). "The ANGPTL6 knockout mice model of ANGPTL6 leads to central obesity, insulin resistance and deposition of fat in the liver and skeletal muscle." (PMID 37810875, 2023). "Taken together, our data and previous findings propose that the increase in ANGPTL6 levels in diabetes is a compensation mechanism in response to insulin resistance." (PMID 32277104, 2020). "Moreover, the basal ANGPTL6 level correlates with insulin resistance as well as fasting insulin levels (Table A2)." (PMID 33668309, 2021).
metabolic syndrome (8 papers, 2014 to 2025). A cluster of metabolic risk factors for CARDIOVASCULAR DISEASES and TYPE 2 DIABETES MELLITUS. "The polymorphism of ANGPTL6 may be closely related to metabolic syndrome." (PMID 37260987, 2023). "Serum ANGPTL-6 levels are significantly higher in patients with metabolic syndrome, particularly in those with increased waist circumference or low HDL cholesterol." (PMID 41026696, 2025). "Patients with the ANGPTL6 rs8112063 CC genotype were less likely to be diagnosed with dyslipidemia by K/DOQI than the bearers of the TT genotype (OR 0.672, 95% CI 0.453–0.997, p = 0.048)." (PMID 36143124, 2022). "ANGPTL6 levels significantly increased before the development of metabolic syndrome and its complications; therefore, measuring ANGPTL6 levels can significantly improve the prediction of metabolic syndrome." (PMID 32277104, 2020). "Serum ANGPTL6 levels have been shown to be significantly higher in patients with metabolic syndrome compared with healthy subjects." (PMID 24478758, 2014). "In this prospective cohort study, serum ANGPTL6 levels in 221 participants without metabolic syndrome were assessed at baseline and were then followed-up after an average of 3 years." (PMID 32277104, 2020). "Moreover, among the components of metabolic syndrome, subjects with high waist circumference or decreased HDL cholesterol had significantly increased serum ANGPTL6 levels." (PMID 24478758, 2014).
gastric cancer (3 papers, 2021 to 2025). A primary or metastatic malignant neoplasm involving the stomach. "Additionally, a report showed that ANGPTL3 and ANGPTL6 expression was lower in gastric cancer (GC) tissues compared to normal gastric tissues, while ANGPTL1, ANGPTL2, and ANGPTL4 were more highly expressed in GC tissues than in normal gastric tissue." (PMID 39708716, 2025). "ANGPTL6 is a secreted angiogenic factor that can promote endothelial cell migration and angiogenesis in AFP-producing gastric cancer." (PMID 36421714, 2022). "Upregulated ANGPTL6 expression resulted in the proliferation of undifferentiated glioblastoma cells, and knockdown of ANGPLT6 in vivo significantly inhibited AFP-producing gastric cancer by regulating endothelial cell migration and tube formation." (PMID 34412629, 2021).
colorectal cancer (2 papers, 2012 to 2022). A primary or metastatic malignant neoplasm that affects the colon or rectum. "ANGPTL6 also drives liver metastasis of colorectal cancer cells." (PMID 36421714, 2022).
glioblastoma (2 papers, 2018 to 2021). The most malignant astrocytic tumor (WHO grade IV). "Moreover up-regulation of ANGPTL6 by miRNA-128 contributes to glioma and glioblastoma multiforme (GBM) resulting in the proliferation of undifferentiated GBM cells." (PMID 29389861, 2018).
intracranial aneurysms (2 papers, 2021 to 2022). "This is a Class III study showing some specificity of presence of the ANGPTL6 gene variant as a marker of familial intracranial aneurysms in a small subset of individuals with familial aneurysms." (PMID 33106390, 2021). "To understand the role of the angiopoietin-like 6 gene (ANGPTL6) in intracranial aneurysms (IAs), we investigated its role in a large cohort of familial IAs." (PMID 33106390, 2021).
type 2 diabetes (2 papers, 2021 to 2022). "However, patients with type 2 diabetes have paradoxically increased circulating ANGPTL6 concentrations compared to healthy individuals." (PMID 36143124, 2022).
chronic hepatitis B (1 paper, 2022). "The results showed that serum ANGPTL6 could effectively differentiate between HBV-related early HCC patients with normal serum alpha-fetoprotein (AFP) levels and the noncancer group (healthy participants and chronic hepatitis B patients) (AUC = 0.717, 95% CI: from 0.614 to 0.805)." (PMID 36421714, 2022).
diabetic nephropathy (1 paper, 2022). "The C allele of ANGPTL6 rs8112063 was also associated with an increased risk of diabetic nephropathy (OR 1.503, 95% CI 1.054–2.143, p = 0.024) and a decreased risk of tubulointerstitial nephropathy as a cause of ESRD in the recessive mode of inheritance (OR 0.349, 95% CI 0.148–0.825, p = 0.012)." (PMID 36143124, 2022).
endothelial dysfunction (1 paper, 2014). In vascular diseases, endothelial dysfunction is a systemic pathological state of the endothelium (the inner lining of blood vessels) and can be broadly defined as an imbalance between vasodilating and vasoconstricting substances produced by (or acting on) the endothelium. "A potential role of ANGPTL6 in endothelial dysfunction is suggested by preliminary results from a recent Finnish study demonstrating that Angptl6 serum levels are higher in women with subsequent pregnancy-induced hypertension." (PMID 24478758, 2014).
gastric adenocarcinoma (1 paper, 2020). "Data from DErrico25 reported downregulated ANGPTL6 level in intestinal‐type gastric adenocarcinoma (FC = −3.797)." (PMID 32410376, 2020).
glioma (1 paper, 2018). A benign or malignant brain and spinal cord tumor that arises from glial cells (astrocytes, oligodendrocytes, ependymal cells). "ANGPTL6 overexpression contributes to proliferation of glioma and GBM." (PMID 29389861, 2018).
high blood pressure (1 paper, 2021). "Therefore, heterozygous ANGPTL6 genetic variants might only exhibit a deleterious effect in combination with certain risk factors such as high blood pressure." (PMID 33106390, 2021).
hypothyroidism (1 paper, 2022). Abnormally low levels of thyroid hormone. "ANGPTL6 is recently being paid attention as it also plays an important role in modulating the risk of dyslipidemia in patients with hypothyroidism." (PMID 34784265, 2022). "Similar to this finding, another research also confirmed that the serum ANGPTL6 concentrations were increased significantly and were positively correlated with the serum levels of thyroid-stimulating hormone and LDL-C under the pathological status of hypothyroidism." (PMID 34784265, 2022).
psoriasis (1 paper, 2016). An autoimmune condition characterized by red, well-delineated plaques with silvery scales that are usually on the extensor surfaces and scalp. "Our study also suggests that ANGPTL6 activation in keratinocytes enhances psoriasis susceptibility." (PMID 27698489, 2016). "Immunofluorescence analysis of skin tissue from one psoriasis patient revealed ANGPTL6 production in epidermal keratinocytes, suggesting they are the source of ANGPTL6 in skin tissue of these patients." (PMID 27698489, 2016). "To assess a potential relationship between ANGPTL6 expression in skin tissue and psoriasis-like conditions, we evaluated phenotypes in K14-Angptl6 Tg mice." (PMID 27698489, 2016). "Further studies are needed to investigate mechanisms by which ANGPTL6 promotes not only psoriasis development but also skin tissue repair in physiological conditions in response to normal skin injury." (PMID 27698489, 2016). "We also observed increased epidermal ANGPTL6 production in some psoriasis patients." (PMID 27698489, 2016). "Finally, we report that ANGPTL6 production is elevated in keratinocytes from some psoriasis patients." (PMID 27698489, 2016). "Finally, we observed enhanced levels of epidermal ANGPTL6 in tissue specimens from some psoriasis patients." (PMID 27698489, 2016). "Our results strongly suggest that increased ANGPTL6 production from keratinocytes contributes to psoriasis pathogenesis and that K14-Angptl6 Tg mice could serve as alternate mouse models of the disease." (PMID 27698489, 2016). "Thus, S100A9 loss in K14-Angptl6 Tg male or female mice did not rescue psoriasis-like skin phenotypes, suggesting that ANGPTL6-dependent psoriasis emerges independently of S100A9 and that these phenotypes are not sex-dependent." (PMID 27698489, 2016). "Thus, elevated ANGPTL6 levels seen in keratinocytes of psoriasis patients support our observations in mice that ANGPTL6 may induce psoriasis-like phenotypes." (PMID 27698489, 2016). "Thus, deletion of macrophages via clodronate liposome treatment may rescue ANGPTL6-dependent psoriasis when skin tissues repeatedly suffer injurious stimuli." (PMID 27698489, 2016). "Finally, we asked whether ANGPTL6 activation is correlated with skin tissue pathologies seen in psoriasis patients." (PMID 27698489, 2016). "We suggest that ANGPTL6-dependent mechanisms associated with psoriasis may be independent of those governed by S100A9." (PMID 27698489, 2016). "To do so, we compared ANGPTL6 protein levels between psoriasis patients and non-psoriasis control subjects." (PMID 27698489, 2016). "By contrast, S100A8 and S100A9 proteins were abundant in skin tissues of all 15 psoriasis patients but not in tissues from any non-psoriasis control subject, suggesting that ANGPTL6 production and S100A8/S100A9 expression are not linked in the pathogenesis of psoriasis." (PMID 27698489, 2016). "Immunohistochemical analysis of tissue specimens with ANGPTL6 antibody revealed abundant or moderate ANGPTL6 protein in the epidermal layer of 13 of 15 tissue specimens from different patients, whereas no ANGPTL6 protein was detected in all 10 non-psoriasis control specimens." (PMID 27698489, 2016).